BACH1 (BACH transcriptional regulator 1)
Diseases named in the same sentence as BACH1 in open-access papers (continued):
Sharing a sentence is not in itself a finding about the gene and the disease.
Anxiety (3 papers, 2025). Intense feelings of nervousness, tension, or panic often arise in response to interpersonal stresses. "The EPM test results implied Bach1 knockdown could alleviate anxiety-like behavior caused by high-altitude hypoxic TBI." (PMID 39905004, 2025).
cervical cancer (3 papers, 2014 to 2024). A primary or metastatic malignant neoplasm involving the cervix. "BACH1 also participates in viral gene transcription and expression, which hints us its connection with some viral-induced tumor, for example, cervical cancer." (PMID 35035660, 2022). "The overexpression of BRCA1, BRCA2, RAD51, BRIP1 (BACH1), FANCD2, BLM and RFC in non-responding versus responding cervical cancer samples suggests that DNA repair mechanism activation occurs through cell cycle arrest and homologous recombination." (PMID 24708616, 2014).
emphysema (3 papers, 2020 to 2022). "Previous studies on this topic indicated that the decrease of Nrf2 in alveolar macrophages and lung tissues of patients with emphysema was due to an increase of Bach-1 and Kelch-like ECH-associated protein 1 or a loss of Nrf2 protein stability." (PMID 32000766, 2020). "Nrf2/KEAP1-BACH1 equilibrium has been identified in pulmonary emphysema patients, whereby high levels of BACH1 and KEAP1 result in reduced stress response, mediated by MAPKs, including JNK and ERK." (PMID 36032081, 2022). "Bach1 expression along with Keap-1 has been shown to be increased in lung tissue and alveolar macrophages in patients with severe emphysema suggesting increased repression of anti-oxidant genes in COPD." (PMID 35441963, 2022).
Fanconi anemia (3 papers, 2013 to 2022). Fanconi anemia (FA) is a hereditary DNA repair disorder characterized by progressive pancytopenia with bone marrow failure, variable congenital malformations and predisposition to develop hematological or solid tumors. "The DNA helicase BRCA1-associated C-terminal helicase/BRCA1-interacting protein 1 (BACH1/BRIP1) is inactivated in patients with Fanconi anemia (FA); BACH1 is also known as FA complementation group (FANCJ)." (PMID 36032672, 2022).
metastatic tumor (3 papers, 2016 to 2024). "RKIP, a downregulator of Bach1 expression, is reduced in the metastatic tumor of CRC." (PMID 27999449, 2016).
Oral Cancer (3 papers, 2024 to 2026). "This analysis revealed that in addition to the positive control GAPDH, all oral cancers (except SCC4) upregulated the miR-155 downstream targets OLFML3, TBR1, BACH1, ZNF652, IRF2-BP2, and ZIC3." (PMID 38396844, 2024).
osteoporosis (3 papers, 2020 to 2025). A condition of reduced bone mass, with decreased cortical thickness and a decrease in the number and size of the trabeculae of cancellous bone (but normal chemical composition), resulting in increased fracture incidence. "Bach1 inhibitors have potential in inhibiting bone destructive diseases such as periodontitis, rheumatoid arthritis and osteoporosis." (PMID 32850850, 2020). "Therefore, Bach1 inhibitors have potential utility in bone destructive diseases, such as osteoporosis, periodontitis, and rheumatoid arthritis." (PMID 32850850, 2020). "Further work will focus on the exact contribution of NFIC, BACH1, CEBPB, and POU2F2 to osteoporosis pathogenesis." (PMID 35757392, 2022). "The core transcription factors in the ceRNA network, NFIC, BACH1, CEBPB, and POU2F2, might be related to osteoporosis." (PMID 35757392, 2022).
osteosarcoma (3 papers, 2021 to 2024). A usually aggressive malignant bone-forming mesenchymal neoplasm, predominantly affecting adolescents and young adults. "In osteosarcoma, BACH1 is induced by circ_0081001 via targeting miR-494-3p to promote proliferation of osteosarcoma cells." (PMID 38321558, 2024). "Similarly, the circ_0000337/miR-4458/BACH1 axis also promotes proliferation in osteosarcoma." (PMID 38321558, 2024).
periodontitis (3 papers, 2020 to 2024). An acute or chronic inflammatory process that affects the tissues that surround and support the teeth. "At the genetic level, it has been reported that the elevated expression of ST8SIA1, a periodontitis risk gene, caused by weakening of Bach1's binding to effect T allele of its coinherited variants is a genetic cause of periodontitis." (PMID 37602966, 2023). "Totally, Sin binds to Bach1, promoting the ubiquitination degradation of Bach1, which leads to improving the levels of oxidative stress and inflammation in periodontitis." (PMID 38734708, 2024). "We observed a significant elevation in Bach1 expression in periodontal tissues with periodontitis and PDLCs under inflammatory conditions." (PMID 37602966, 2023). "Our study is expected to reveal Bach1 as a potential target for cell‐based periodontal regeneration in periodontitis treatment." (PMID 37602966, 2023). "The differences in Bach1 expression between periodontitis and healthy periodontal tissues were proven in human periodontal ligament tissue, the periodontium of rats, and PDLCs under inflammatory and normal conditions." (PMID 37602966, 2023). "Bach1 expression in human periodontal tissues of healthy teeth and teeth with periodontitis was evaluated by immunohistochemistry." (PMID 37602966, 2023). "The percentage of Bach1‐positive cells was significantly higher in periodontal tissues with periodontitis than in the healthy group (p < 0.01)." (PMID 37602966, 2023). "In this study, our results indicated that the expression level of the oxidative stress‐related factor Bach1 was significantly increased in periodontal tissues of periodontitis." (PMID 37602966, 2023). "Overall, Sin could be a promising drug candidate for the treatment of periodontitis by targeting binding to Bach1." (PMID 38734708, 2024). "Collectively, these findings indicated that Bach1 was induced and might be an important regulator in the pathogenesis of periodontitis." (PMID 37602966, 2023). "Bach1 could be a promising target for enhancing periodontal tissue regeneration under periodontitis conditions." (PMID 37602966, 2023). "Moreover, we explored the mechanism of Sin targeting Bach1 in the rat periodontitis model." (PMID 38734708, 2024). "Therefore, Bach1 could be a promising target for enhancing periodontal tissue regeneration under periodontitis conditions." (PMID 37602966, 2023). "Therefore, in the present study, we evaluated Bach1 expression in periodontitis tissue and PDLCs." (PMID 37602966, 2023). "Given that the ages of donors between the healthy and periodontitis groups could not be matched in human tissues, we also detected Bach1 expression in an experimental periodontitis model in rats, and contralateral periodontal tissue served as a healthy self‐control." (PMID 37602966, 2023).
rheumatoid arthritis (3 papers, 2020 to 2025). A chronic, systemic autoimmune disorder characterized by inflammation in the synovial membranes and articular surfaces. "The study identifies BACH1 as a key driver of fibroblast-like synoviocyte pathogenicity in rheumatoid arthritis, highlighting its role in regulating fatty acid metabolism and ferroptosis." (PMID 39467637, 2025).
Arthritis (2 papers, 2024 to 2025). Inflammation of a joint. "Finally, transcription factor motif enrichment analysis revealed transcription factors such as Rela, Relb, Junb, Nfe2l2, and Bach1 that could regulate the expression of Mir221/222 in arthritis." (PMID 39235454, 2024). "In addition to the BACH1 discovery, the highest ranked TFs in RA FLS included two homeobox genes (NKX2-1 and HOXA1) not previously implicated in arthritis." (PMID 39467637, 2025).
B cell lymphoma (2 papers, 2024 to 2025). "The endogenous regulation of BACH1 protein amount by FBXO22 was further examined by using human B cell line Namalwa cells derived from B cell lymphoma." (PMID 38673728, 2024). "When the human B cell line derived from B cell lymphoma was treated with the TBK1 inhibitors, BACH1 protein amount was increased, suggesting the universality of BACH1 protein regulation by TBK1." (PMID 38673728, 2024).
cardiac hypertrophy (2 papers, 2023 to 2025). "It indicates that BACH1 is a significant regulatory factor in pathological cardiac hypertrophy through its control of AT1R expression and the Ca2+/CaMKII pathway." (PMID 39887888, 2025). "Targeting BACH1 shows great promise as an innovative approach to prevent and treat pathological cardiac hypertrophy and heart failure." (PMID 39887888, 2025). "Additionally, in an in vitro cardiac hypertrophy model, BACH1 overexpression stimulates the growth of cardiomyocytes treated with Ang II and norepinephrine while silencing BACH1 attenuates this effect." (PMID 39887888, 2025). "In addition, upregulation of BACH1 mediated activation of CaMKII was proven to accelerate cardiac hypertrophy and fibrosis." (PMID 37891701, 2023).
colon adenocarcinoma (2 papers, 2020 to 2022). "There are 3 cases of R538Q with BACH1 mutation, 2 cases of READ (Rectum adenocarcinoma), and 1 case of COAD (Colon adenocarcinoma)." (PMID 35651942, 2022).
COVID-19 (2 papers, 2024 to 2025). A disease caused by infection with severe acute respiratory syndrome coronavirus 2. "Moreover, we identified that more than half of the Mon IFI30 marker peaks were shared with monocytes from infants affected with COVID-19, and BACH1, NFE2L2, FOS, and FOSL2 are the master regulators of the cell state." (PMID 39712003, 2024).
dementia (2 papers, 2019 to 2020). Loss of intellectual abilities interfering with an individual's social and occupational functions. "Hence, in our opinion, the conclusions about the strong association between miR-155/BACH1 and the development of dementia in DS require more extensive investigation." (PMID 32839417, 2020). "Recent evidence suggests that DS dementia strongly correlates with overexpression of miR-155 on chromosome 21 with concomitant reduction of multiple CNS-functional targets, including BACH1, CoREST1, Cyclin D1, BCL6, BCL10, BIM, and SAPK4." (PMID 31824553, 2019). "DS dementia strongly correlates with overexpression of miR-155 on chromosome 21 with concomitant reduction of multiple CNS-functional targets, including BACH1, CoREST1, Cyclin D1, BCL6, BCL10, BIM, and SAPK4." (PMID 31824553, 2019). "Reduced BACH1 levels in DS with dementia with respect to AD samples were also observed." (PMID 32839417, 2020). "In this review, we discuss the physiological relevance of BACH1/Nrf2 signaling in the brain and how the dysfunction of this system affects the redox homeostasis in DS neurons and how this axis may contribute to the transition of DS into DS with AD neuropathology and dementia." (PMID 32839417, 2020).
Ewing sarcoma (2 papers, 2024 to 2025). A small round cell tumor that lacks morphologic, immunohistochemical, and electron microscopic evidence of neuroectodermal differentiation. "In Ewing sarcoma, BACH1 downregulates EWSR1, an RNA-binding protein that mediates the transcription percent of cell cycle protein D1a and D1b by raising the transcription elongation rate of Ewing sarcoma cells." (PMID 38321558, 2024). "In the analysis of H3K27ac ChIP-seq data from Ewing sarcoma (EWS), we find that BACH1, OTX2, and KNCH2 might affect EWS prognosis by binding to promoter and enhancer regions across the genome." (PMID 40210440, 2025).
gallbladder cancer (2 papers, 2021 to 2023). "BACH1 directly represses the expression of a subset of proteasome genes in gallbladder cancer and cholangiocarcinoma cells." (PMID 34339740, 2021).
gastric cancer (2 papers, 2024 to 2025). A primary or metastatic malignant neoplasm involving the stomach. "Liu has identified that CA, DCA, and CDCA significantly activate the FXR receptor, resulting in the increased expression of BTB and CNC homology 1 (BACH1), glutathione (GSH) synthetase, and GPX4 in gastric cancer cells of HGC-27 and MKN-45 in a ferroptosis-dependent manner." (PMID 39769418, 2024).
Hepatic steatosis (2 papers, 2023). Steatosis is a term used to denote lipid accumulation within hepatocytes. "Histological studies showed that Bach1 overexpression aggravated HFD-induced hepatic steatosis." (PMID 38129407, 2023). "A methionine-choline deficient (MCD) diet was fed to wild type (WT) and BACH1(−/−) mice and the WT mice were shown to develop evident hepatic steatosis with a six-fold increase in hepatic triglyceride content; however, BACH1(−/−) mice exhibited negligible hepatic steatosis." (PMID 37228820, 2023). "Altogether, these data indicated that hepatocyte-specific deletion Bach1 improved insulin signaling and dysregulation of glucose homeostasis in HFD-fed mice, and protected from HFD-induced liver steatosis." (PMID 38129407, 2023).
hyperglycaemia (2 papers, 2022 to 2023). "Hepatic BACH1 knockdown ameliorates hyperglycemia and improves insulin sensitivity in diabetic male mice." (PMID 38129407, 2023).
inflammatory bowel disease (2 papers, 2021 to 2023). A spectrum of small and large bowel inflammatory diseases of unknown etiology. "Moreover, a study investigating the role of Bach1 (repressor of HO-1 expression) in inflammatory bowel disease has identified that macrophages from Bach1-deficient mice exhibit an M2 profile (i.e., expression of M2 markers such as Arg1, Ym1, and Fizz1) with concomitant HO-1 overexpression." (PMID 33809696, 2021).
ischemic stroke (2 papers, 2023 to 2024). A stroke disorder caused by obstruction of blood flow to the brain, due to thrombotic (local blood clot formation) or embolic (due to a blood clot or other material traveling from another site) event. "Subsequent in vivo experiments are necessary to confirm the effect of rESWT on Bach1 expression in ischemic stroke rat brains and to develop a model of Bach1 overexpression, enabling a more detailed assessment of the interactions among molecular pathways." (PMID 38777838, 2024). "Here, we employed bioinformatics techniques to demonstrate that Bach1 was overexpressed in patients suffering from ischemic stroke." (PMID 38777838, 2024). "While TFs are difficult to target pharmacologically, chemical compounds that could downregulate BACH1 may be an alternative for modulating microglial function in the treatment of ischemic stroke." (PMID 38082331, 2023).
myeloid leukemia (2 papers, 2013 to 2020). A clonal proliferation of myeloid cells and their precursors in the bone marrow, peripheral blood, and spleen. "We compared Bach1 protein levels between C2C12 cells and myeloid leukemia cell line M1 cells and found that the amount of Bach1 protein was more in M1 cells than in C2C12 cells which were induced toward muscle cell differentiation for 6 days." (PMID 32776961, 2020). "For example, increased expression of BACH1 (transcriptional regulator of megakaryocytic differentiation process) and SON (homologous sequence with MYC family of oncoproteins) were reported in association with myeloid leukemia in DS." (PMID 23343470, 2013).
myocardial ischemia (2 papers, 2016 to 2024). A disorder of cardiac function caused by insufficient blood flow to the muscle tissue of the heart. "For example, miR-125b reduces myocardial infarct size and inhibits myocardial ischemia‒reperfusion injury, and miRNA-30c-5p prevents MI/RI by regulating Bach1/Nrf2." (PMID 38172743, 2024). "In addition, genetic ablation of Bach1 leads to up-regulation of HO-1 in myocardial ischemia/reperfusion and SCI in mice." (PMID 26925775, 2016).
Parkinson's (2 papers, 2022 to 2025). "The study by Ahuja and co-workers convincingly demonstrates that Bach1 ablation has a pronounced neuroprotective effect in MPTP-induced parkinsonism and that Bach1 inhibition could serve as a drug target to prevent PD pathology." (PMID 36139853, 2022).
porphyria (2 papers, 2013 to 2014). Porphyria is a group of diseases in which substances called porphyrins build up, negatively affecting the skin or nervous system. "Thus, we hypothesize that under heme-deficient conditions, such as in porphyria, the Bach1-MafK heterodimer binds to the MARE sites of exocrine pancreatic zymogens and represses their transcription." (PMID 24652768, 2014). "It is tempting to speculate that our study also provides a new therapeutic target for these porphyria individuals – for instance, the possibility of knocking down BACH1 specifically in the exocrine pancreas to enhance zymogen levels, thereby, alleviating acute episodic abdominal pains." (PMID 24652768, 2014). "For example, BACH1 is negatively regulated by hemin, an FDA-approved drug used to treat porphyria (Panhematin®, Lundbeck Inc, Deerfield, IL)." (PMID 24349199, 2013).
pulmonary alveolar proteinosis (2 papers, 2018 to 2024). A rare lung disorder characterized by the filling of the pulmonary alveoli with proteinaceous material which stains positive with periodic acid-Schiff stain. "Research by the same group has shown that the degree of pulmonary alveolar proteinosis is more severe in Bach1/Bach2 double KO mice, but absent in Bach1 KO mice." (PMID 29463401, 2018).
sarcoma (2 papers, 2022 to 2024). A usually aggressive malignant neoplasm of the soft tissue or bone. "We further validated the BACH1 dependency in Keto diet–induced tumor metastasis using a mouse sarcoma model." (PMID 38838145, 2024).
Thrombocytopenia (2 papers, 2018 to 2025). A reduction in the number of circulating thrombocytes. "Impaired megakaryocyte maturation and thrombocytopenia occur when BACH1 is overexpressed in transgenic mice, regulated by the GATA1 promoter." (PMID 39887888, 2025).
atopic dermatitis (1 paper, 2020). "Altogether, our study identifies BACH1 as a molecular target for CBD in keratinocytes and sets the basis for the use of topical CBD for the treatment of different skin diseases including atopic dermatitis and keratin disorders." (PMID 31518892, 2020). "Our validation of CBD as an BACH1 inhibitor suggests that CBD treatment would a) protect the skin against external insults: e.g. against UVA-irradiation-induced damage; and b) be greatly beneficial in a variety of skin conditions, e.g. eczema or atopic dermatitis." (PMID 31518892, 2020).
carcinoid (1 paper, 2014). "let-7 overexpression inhibited growth of carcinoid cell lines, and let-7 inhibition increased protein content of the transcription factor BACH1 and its targets MMP1 and HMGA2, all known to promote bone metastases." (PMID 25546138, 2014).
cervical tumors (1 paper, 2014). "Increased protein levels of FANCD2, RAD51, BRCA1, and BRIP 1 (BACH1) in NCR compared to CR cervical tumors groups were confirmed on the validation set." (PMID 24708616, 2014).
cholestasis (1 paper, 2023). Impairment of the bile flow caused by obstruction within the liver, or outside the liver in the bile duct system. "In HCV, DILI, cholestasis, IBD, IR injury and other diseases, BACH1 transcriptionally inhibits HO-1 to mediate oxidative stress response, which causes aggravated organ function damage and a rise in related indicators." (PMID 37228820, 2023).
chronic hepatitis C (1 paper, 2014). "Our results do not support the importance of Bach-1 in repression of HMOX1 in patients with chronic hepatitis C." (PMID 24752012, 2014).
chronic obstructive pulmonary disease (1 paper, 2024). A chronic and progressive lung disorder characterized by the loss of elasticity of the bronchial tree and the air sacs, destruction of the air sacs wall, thickening of the bronchial wall, and mucous accumulation in the bronchial tree. "The link between NRF2 and BACH1 plays a crucial role in the pathogenesis of diseases such as cancer and chronic obstructive pulmonary disease (COPD)." (PMID 38542492, 2024).
cutaneous melanoma (1 paper, 2022). A primary melanoma arising from atypical melanocytes in the skin. "In addition, BACH1 in the Skin Cutaneous Melanoma (SKCM) metastatic tumor tissue was significantly higher than that in the SKCM tumor tissue (p < 0.001)." (PMID 35651942, 2022).